TERT (telomerase reverse transcriptase)
Diseases named in the same sentence as TERT in open-access papers (continued):
Sharing a sentence is not in itself a finding about the gene and the disease.
meningioma (continued). "Along with TERT promoter mutations, CDKN2AB alterations are now included in categorizing grade III meningiomas." (PMID 36686824, 2022). "In particular, hotspot mutations (C228T and C250T) in the TERT promoter were detected in 20% of WHO grade 3 meningiomas compared to 1.7% and 5.7% of grade 1 and 2 meningiomas, respectively, and in 6.4% in a large cohort of meningiomas." (PMID 36230612, 2022). "TERT C228T and C250T mutations are typically found in WHO grade 1 meningiomas and are associated with a higher tendency to a malignant evolution." (PMID 35892898, 2022). "Data published recently have also shown that activating TERT promoter mutations, frequent inactivation of BAP1, deletions of CDKN2A/B, and mutations in DMD are frequent in meningiomas with malignant histological progression." (PMID 34778063, 2021). "In large-scale genomic studies of meningioma, higher grade (WHO grade II and III) meningioma were in some studies exclusively related to pathogenic variants in NF2, associated with mutations in the TERT promoter, and deletion of 1p and CDKN2A." (PMID 33262459, 2021). "More recent studies have also shown an association of molecular profiles with meningioma recurrence and progression, e.g., TERT (telomerase reverse transcriptase) promoter mutation, DNA methylation profile, or loss of histone H3K27me3." (PMID 33674888, 2021). "More recently, mutations in TERT (telomerase reverse transcriptase) and CDKN2A (cyclin-dependent kinase inhibitor 2A) have been shown to be potential prognostic indicators in higher grade meningiomas." (PMID 34300316, 2021). "In large-scale genomic studies of meningioma, HGMs were in some studies exclusively related to pathogenic variants in NF2, associated with mutations in the TERT promoter." (PMID 34778063, 2021). "Next, we focused on the most common genetic alterations reported so far in meningiomas, including the NF2, SMARCB1, as well as TRAF7, AKT1, SMO, KLF4, PIK3CA, and TERT in non-NF2 mutated meningiomas." (PMID 31470906, 2019). "Next, we focused on the most prevalent genetic alterations reported in meningiomas so far, including NF2, SMARCB1, as well as TRAF7, AKT1, SMO, KLF4, PIK3CA, and TERT in non-NF2 mutated meningiomas." (PMID 31470906, 2019). "We also performed Sanger sequencing to check for the presence of mutations previously reported in meningioma driver genes, including regions of NF2, AKT1, TRAF7, KLF4, SMO, and the TERT promoter." (PMID 28552950, 2017). "Stratification for TERT alterations should be adopted in future clinical trials of progressive/higher-grade meningiomas." (PMID 29312603, 2017). "We identified a novel chromosomal rearrangement involving TERT in a recurrent WHO grade III meningioma sample (patient 13)." (PMID 29312603, 2017). "The rationale for not testing TERT promoter mutations in meningiomas is the absence of TERT promoter mutations in low‐risk meningiomas, and the integrated score based on the 2021 WHO classification is most accurate in risk prediction." (PMID 40356449, 2025). "A further limitation is (v) the unavailability of TERT promoter mutation data, as this is not routinely tested in Grade 1 or 2 meningiomas." (PMID 40356449, 2025). "Moreover, predictors for preoperative seizures were assessed in the subgroup of meningiomas WHO grade 2 and 3 with available TERT promotor mutation (n = 67)." (PMID 38581569, 2024). "Further studies on the mechanisms regulating TERT hyperactivity in meningiomas are thus needed." (PMID 36836440, 2023). "In this WHO classification, loss of H3K27me3 is indicative of aggressive meningioma behavior and recurrence, and homozygous deletions of CDKN2A/B and mutations of TERT promoter (pTERT) are criteria for Grade 3 meningiomas since they are linked to an increased risk of recurrence." (PMID 38001599, 2023).
meningioma (continued). "Another part is related to the degree of tumor malignancy, such as the deletion of histone H3 K27me3 expression is closely associated with meningioma recurrence, TERT promoter mutation and CDKN2A/B pure deletion are molecular biological markers of CNS WHO grade 3 meningioma." (PMID 36969005, 2023). "In particular, the lack of TERT promoter mutations is the main characteristic of de novo grade 2 meningiomas, in contrast with the occurrence of TERT promoter mutations in secondary grade 2 meningiomas that have recurred from grade 1." (PMID 35565385, 2022). "Furthermore, 8% harbored mutations in TERT, CDKN2A/B, or BAP1 of which 6% occurred in grade 1 meningiomas." (PMID 35299730, 2022). "However, the heterogeneity of mechanisms of increase in TERT activity in meningiomas is the main limitation to its use as a prognostic marker." (PMID 36232992, 2022). "Those formerly diagnosed as grade 3 meningiomas (7 cases) did not present a positive TERT promoter mutation." (PMID 35774130, 2022). "TERT promoter mutations also occur mostly (although not exclusively) in NF2-altered meningioma and, although uncommon, are highly associated with grade and decreased time to recurrence/progression." (PMID 36230612, 2022). "Interestingly, most cases with sequence alterations in BAP1, CDKN2A/B, and TERT occurred in meningiomas with a low-grade cytogenetic background." (PMID 35299730, 2022). "Mutations in the TERT promoter have been associated with worse prognosis and decreased survival rates in grade II and III meningiomas, and CDKN2A mutation or gene deletion has been associated with meningioma recurrence." (PMID 34300316, 2021). "In contrast, we could not find in our WHO grade 1 tumors and control populations, non-synonymous genetic variants, for other genes previously reported to be recurrently mutated in meningiomas such as the TRAF7, AKT1, KLF4, TERT, and PIK3CA genes." (PMID 34868937, 2021). "Surprisingly, despite the high frequency of aggressive meningioma subtypes, especially atypical meningiomas, no TERT promoter mutations were detected." (PMID 34495383, 2021). "Forty-six patients suffered from a tumor other than meningioma, and no TERT mutation was detected in these patients." (PMID 33674888, 2021). "Finally, only one TERT mutation (A279T) was detected in one WHO°I tumor, which differs from the previously reported TERT alterations in meningiomas (C228T and C250T)." (PMID 31470906, 2019). "Finally, the TERT A279T mutation was found in our IVM cohort, which deviates from the previously reported TERT mutations in meningiomas (C228T and C250T)." (PMID 31470906, 2019). "TERT promoter was found to be mutated in approximately 7% of grade II/III meningiomas and its presence was associated with a strongly negative prognostic value on overall survival." (PMID 30279357, 2018). "A larger screen of 27 recurrent atypical meningiomas (non-paired) identified 2 additional samples, suggesting approximately 13% (4/31) of progressed atypical samples harbour mutations in the TERT promoter." (PMID 28195122, 2017). "To assess whether TERT gene rearrangements were present in progressive higher-grade meningiomas, we performed targeted RNA fusion gene analysis in TERTp wild-type meningioma cases (n=28) using Anchored Multiplex PCR (AMP)." (PMID 29312603, 2017). "Thus, we believe co-occurring mutations other than chromosome 1p loss, TERT mutation, CDKN2A/B loss can stratify NF2 mutated meningiomas, although a larger data set is required to confirm this hypothesis." (PMID 40562609, 2025). "They further reported no TERT promoter mutations, a marker of aggressive meningioma in adults." (PMID 39612013, 2024).
meningioma (continued). "Given the low frequency of TERT promotor mutations in meningiomas in general and in grade 1 lesions in particular, the current WHO classification recommends “consideration (of TERT sequencing) in clinically aggressive atypical meningiomas or those with borderline CNS WHO grade 2/3 features”." (PMID 37686690, 2023). "TERT promoter mutations have been correlated with shorter, progression-free survival in a retrospective series of 252 meningiomas, with 10.1 months in patients with TERT promoter mutations, compared with 179 months in patients without a TERT promoter mutations regardless of the histological grading." (PMID 35565385, 2022). "Furthermore, the loss of function of dystrophin-encoding and muscular dystrophy-associated gene (DMD) has been considered an additional negative prognostic factor in TERT-mutated meningiomas." (PMID 35565385, 2022). "The mutational spectrum of atypical meningiomas is mainly characterized by NF2 mutations that co-occur with genomic instability or recurrent SMARCB1 mutations in primary atypical meningiomas, and with TERT promoter mutations in secondary (i.e., arisen from the progression of benign tumors) ones." (PMID 33670055, 2021). "Furthermore, telomerase reverse transcriptase (TERT) promoter mutations have never been detected in de novo atypical meningiomas but are present in secondary atypical meningiomas progressed from lower-grade primary tumors." (PMID 34679551, 2021). "However, TERT promoter mutation was absent in patients harboring both meningioma and unrelated tumor disease." (PMID 33674888, 2021). "Importantly, these primary atypical meningiomas do not harbour TERT promoter mutations, which have been reported in atypical tumours that progressed from benign ones." (PMID 28195122, 2017). "We now recognize that patients with meningiomas harboring CDKN2A homozygous deletion or TERT promoter mutation regardless of histologic grade have poor clinical outcomes similar to patients with histologically diagnosed anaplastic (CNS WHO grade 3) meningiomas." (PMID 36723772, 2023). "Additionally, a DNA methylation–based classification and TERT promoter mutation status analysis are among the most promising advances with the potential to further refine the prognostic evaluation of meningiomas but currently do not provide a target for treatment." (PMID 34601710, 2022). "As our study commenced prior to the publication of WHO CNS 5, meningioma grading was based solely on histopathology without integrated molecular profiling (H3K27me3, TERT promoter, CDKN2A/B status undetermined)." (PMID 41358608, 2025). "This held true when only comparing patients with and without preoperative seizures in the subgroup of meningiomas WHO grade 2 and 3 with available TERT promotor mutation status (OS: 65 versus 124 months, p = 0.805; RFS: 56 versus 34 months, p = 0.670)." (PMID 38581569, 2024). "A meta-analysis investigating data from 677 patients revealed that TERT alterations predicted progression-free survival independent of the WHO grades in meningiomas." (PMID 37370707, 2023). "The chordoid meningiomas showed lower rates of mutation than non-chordoid high grade meningiomas, with infrequent NF2 and TERT promoter mutations." (PMID 35440040, 2022). "Assessment of TERT promoter status has now been added as a criterion for a diagnosis of CNS WHO grade 3 meningioma independent of the histopathological findings." (PMID 36230612, 2022).
meningioma (continued). "The 2021 update additionally reports commonly altered genes in meningiomas, but largely does not use them as grading criteria with the exception of CDKN2A/B homozygous deletion and TERT promoter mutation as diagnostic for grade 3 meningiomas." (PMID 36033542, 2022). "Although the investigators detected no mutation in grade I meningiomas, 4% and 16% of subjects with grade II and III meningiomas had TERT promotor mutations, respectively." (PMID 34235021, 2021). "Meningioma with TERT alterations, regardless of WHO grades or pathological subtypes, had a highly significant risk of recurrence." (PMID 34778063, 2021). "NF2 mutations were found in 44% of the cases, while common genetic alterations in meningiomas of other locations (TRAF7, AKT1, SMO, KLF4, PIK3CA, and TERT) were lacking in non-NF2-associated cases." (PMID 31470906, 2019). "Other studies have demonstrated the negative prognostic role of TERT mutations regardless of the WHO grading, suggesting that TERT-mutated meningiomas should be followed carefully, or treated aggressively, and include TERT analysis in the routine diagnostic assessment." (PMID 35565385, 2022). "Two meningioma cell lines, IOMM-Lee and CH-157 MN, harbor the C228T hotspot TERT promoter mutation and could be useful to develop and test TERT inhibitors given their current lack of clinical testing." (PMID 30082628, 2018). "Importantly, when we screened our cohort of 110 primary, non-recurrent meningiomas (n=66 NF2 atypical, n=12 NF2 benign CNV-high, n=4 non-NF2 benign, CNV-high, n=12 NF2 benign CNV-low, n=12 non-NF2 benign CNV-low and n=4 NF2/SMARCB1), we did not identify any TERT promoter mutations." (PMID 28195122, 2017). "Although TERT promoter mutations and CDKN2A/B deletions are known to confer WHO grade III meningiomas in the latest WHO grades for CNS tumours, we did not evaluate the respective molecular analyses (TERT promoter and CDKN2A/B deletion) and utilised the 2016 WHO classifications." (PMID 37752594, 2023).
hepatocellular carcinoma (104 papers, 2000 to 2025). A malignant tumor that arises from hepatocytes. "Telomerase reverse transcriptase (TERT) is activated to drive the occurrence of hepatocellular carcinoma as an inserted target of hepatitis B virus in hepatitis B virus-associated hepatocellular carcinoma." (PMID 40083328, 2025). "For example, fructose-1,6-bisphosphatase 1 (FBP1) acts as a protein phosphatase to dephosphorylate TERT S227, inducing cell senescence, and its deficiency promotes tumor growth in hepatocellular carcinoma." (PMID 41213904, 2025). "A novel TERT c.2062 C > G mutation, encoding the Glu668Asp variant, was also identified in the neoplastic tissue of a patient with hepatocellular carcinoma, who had idiopathic familial pulmonary fibrosis and familial cryptogenic cirrhosis." (PMID 39849589, 2025). "Hotspot mutations in the promoter of telomerase reverse transcriptase (TERT) gene are the most common genetic variants in hepatocellular carcinoma (HCC) and associated with poor prognosis of the disease." (PMID 38769666, 2024). "By observation, the TERT*(rs2736098; c.915G > A) and TERT*(rs2736100; c.1574-3777G > T) variants exhibited a significant difference with an elevated risk of hepatocellular carcinoma." (PMID 37884663, 2023). "Several meta-analysis reports investigated the association of the TERT gene variants with the susceptibility for hepatocellular carcinoma, but with challenging interpretations." (PMID 37884663, 2023). "Detection of TERT promoter mutations in circulating tumour DNA of patients with hepatocellular carcinoma is associated with shorter survival and proposed as useful biomarker of poor prognosis in patients with advanced liver cancers." (PMID 38033865, 2023). "The silencing of the NHP2 gene caused a decrease in of TERT expression, destabilization of the telomerase complex and inhibition of the proliferation of hepatoma cells overexpressing HBx." (PMID 36358677, 2022). "Activating mutations in the promoter region of TERT (TERTp) gene are frequently observed in low- and high-grade dysplastic nodules and defined as early events in hepatocellular carcinoma development." (PMID 34359670, 2021). "The current meta-analysis revealed that the TERT rs2736098 AA genotype was significantly associated with an increased risk of hepatocellular carcinoma in the heterozygous and dominant models." (PMID 29695979, 2018). "TERT promoter mutations have been identified in numerous other cancers such as thyroid, bladder, hepatocellular cancer and malignant glioblastoma." (PMID 29108273, 2017). "TERT promoter-activating mutations were recently identified as a novel mechanism to activate telomerase in hepatocellular carcinoma (HCC) and many other malignancies." (PMID 28416747, 2017). "Telomerase reverse transcriptase (TERT) promoter mutations are among the most frequent noncoding somatic mutations in multiple cancers, including hepatocellular carcinoma (HCC)." (PMID 27056898, 2016). "Of 109 patients with hepatocellular carcinoma, 41 (39.0%) and 15 (14.6%) harbored TERT and CTNNB1 mutations, respectively." (PMID 27661004, 2016). "In two cases, discordance in TERT promoter mutation status was observed between the primary and the corresponding recurrent hepatocellular carcinoma." (PMID 27661004, 2016). "This is similar to that observed in hepatocellular carcinomas where the TERT promoter mutation is significantly more frequent in patients without hepatitis virus B infection." (PMID 25301727, 2014). "BARD1 mutation is reported in 1.1% of hepatocellular adenomas, SGK1 mutation is observed in numerous tumor types, and TERT is also one of the most commonly mutated genes in hepatocellular carcinoma, with mutations predominantly in the reporter region that regulates gene expression, as in this case." (PMID 38903310, 2024).